STAT3 (signal transducer and activator of transcription 3)
Diseases named in the same sentence as STAT3 in open-access papers (continued):
Sharing a sentence is not in itself a finding about the gene and the disease.
cancer (continued). "STAT3 has attracted a lot of attention as a cancer therapeutic target in several cancers, such as ovarian cancer, neck squamous cell carcinoma, and cervical cancer." (PMID 33706784, 2021). "The involvement of STAT3 in the development, metastasis, multidrug resistance, and proliferation of cancer has been subject to extensive research." (PMID 34488773, 2021). "IL6-JAK2/STAT3 signaling pathway is one of the most typical oncogenic signaling pathways in cancers." (PMID 33768003, 2021). "Taken together, these data unequivocally confirmed that CAFs-secreted IL-6 induced LRG1 expression through downstream activation of JAK2/STAT3 signaling in cancer cells." (PMID 34930899, 2021). "IL-6 is an inflammatory factor widely reported to be involved in several pathological networks in cancer, and is also recognized as an activator of the STAT3 signalling pathway." (PMID 33855091, 2021). "An inflammatory regulatory network mediated by the joint action of NF-κB, STAT3, and AP-1 factors at common target sites is critical for transformation in our inducible model, and this network is involved in many human cancers." (PMID 34463254, 2021). "We also observed that anti-cancer activities of W2014-S was significantly attenuated in A549 cells in which STAT3 was knocked out by Crispr/cas9 system." (PMID 33391507, 2021). "Despite some authors having labelled STAT3 an “undruggable” factor, several agents have now been developed to block its expression or function that have shown promise in pre-clinical cancer studies." (PMID 34834425, 2021). "These regulatory mechanisms allow STAT3 to exert its physiological functions and limit the aberrant signaling seen in cancer." (PMID 34067421, 2021). "STAT3 can prevent autophagy and apoptosis and promote invasion and migration of primary cancers, such as HCC." (PMID 33804548, 2021). "Immunoblot analysis showed that the phosphorylation levels of JAK2 and STAT3 in cancer cells were down-regulated by matrine." (PMID 34642304, 2021). "STAT3 plays an important role in tumorigenesis and in progression of cancer, which allows STAT3 to arise as a promising molecule target in the treatment of cancer." (PMID 33804548, 2021). "The anti-cancer properties of verbascoside can be due to its suppressive effects on multiple cellular signaling pathways, such as NF-κB, STAT3, and TGF-β signaling." (PMID 34575983, 2021). "OSM-SMI-10B, a derivative of OSM-SMI-10 (patent pending) was subsequently synthesized and identified as a hit based on its ability to significantly reduce OSM-induced STAT3 phosphorylation in cancer cells upon co-incubation with OSM as measured by ELISA44." (PMID 34376712, 2021). "STAT3 expression was previously correlated with anoikis resistance, aggressive invasion, and migration capability in cancer 21-23." (PMID 34234852, 2021). "For example, STAT3 regulates mitochondrial functions to drive malignant transformation in certain forms of cancer." (PMID 33420372, 2021). "Napabucasin (BBI608), a small molecule that blocks stem cell activity in cancer cells by targeting the STAT3 pathway, is currently in clinical Phase I/II in combination with TMZ in adult patients with recurrent or progressed GBM (NCT02315534)." (PMID 33918704, 2021). "Various studies have suggested that panobinostat is closely related to the suppression of cancer progression that is mediated by the regulation of several signaling pathways, including STAT3, EGFR, and RAF/ERK." (PMID 34073071, 2021). "As Anxa2 expression and phosphor-Tyr23 are largely evaluated in various cancer types, this regulatory mechanism towards STAT3 somehow outstands as an assignable target for STAT3 inhibition." (PMID 34502195, 2021). "Cytokines, such as IL-6, IL-17 and IL-23 produced by the NF-κB or STAT3 signaling pathway, induce cancer proliferation and metastasis by promoting TAMs to inhibit a cytotoxic T cell response." (PMID 34683963, 2021).
cancer (continued). "Since CD44+CD24– stem cell-like TNBC phenotype and PD-L1 upregulation require STAT3 signaling, these studies support our findings that the STAT3-activating property of PARPi can promote cancer progression and immunosuppression." (PMID 34956861, 2021). "STAT3 has been established as a critical regulator of context-dependent processes in cancer cells and their surrounding stromal cells." (PMID 34440220, 2021). "The STAT3 N‐terminal domain is vital for function and contains a 4‐helix bundle that is a potential target for cancer therapy." (PMID 33382511, 2021). "Regarding angiogenesis, STAT3 is activated in cancer cells by reactive oxygen species (ROS), mechanistic target of rapamycin complex 1 (mTORC1) and/or IL-6, and further induces hypoxia-inducible factor 1-alpha (HIF-1a) activation during hypoxia." (PMID 34440220, 2021). "It was reported that VEGF-A-induced excessive activation of Janus kinase 2/Signal transducer and activator of transcription 3 (Jak2/STAT3) signaling contributes to the abnormal myeloid cell differentiation in cancer." (PMID 34149730, 2021). "Several reports highlight that Signals Transducers and Activators of Transcription 3 (STAT3) is involved in cancer radioresistance." (PMID 34141616, 2021). "STAT3, highly active in more than 50% of BCs, has been described as a key signalling orchestrator of many of the cancer-promoting effects exerted by IL6, but also IL11, LIF and OSM." (PMID 34834425, 2021). "STAT3 is of particular interest because of its involvement in cancer progression and development of drug resistance." (PMID 34680055, 2021). "Targeting STAT3 was found to block TEC activation by cancer cells in metastatic brain sites and thereby suppress metastasis formation." (PMID 34834295, 2021). "STAT3 is closely related to the occurrence of cancers and is an attractive therapeutic target for oncology and drug development." (PMID 34066442, 2021). "Inhibiting JAK2 reduces cell proliferation and induces apoptosis in cancer cells because of inhibition of the phosphorylation of the JAK2 substrates STAT3 and STAT5." (PMID 33503825, 2021). "Integrin ligands induce STAT3 translocation to mitochondria for stimulating OXPHOS function and recently, was described that ECM-integrin-FAK-STAT3 signaling promotes migration in cancer cells." (PMID 34733852, 2021). "Two examples of this are through the activation of STAT3, a transcription factor that is well documented in cancers." (PMID 34350123, 2021). "The suppression of nintedanib-refractory STAT3 hyperactivation by concurrent treatment with the STAT3i silibinin promoted synergistic anti-cancer effects." (PMID 34439322, 2021). "Since hyper-activation of the JAK/STAT3 signaling pathway promotes survival of cancer cells, we investigated the proliferation, migration, and survival status of SW480 cells with STAT3del in comparison with the wild-type SW480 cells." (PMID 33535185, 2021). "STAT3 has become a crucial target for cancer immunotherapy and inhibiting STAT3 can help improve the effects of various immunotherapies." (PMID 34943817, 2021). "The dual inhibition of STAT1 and STAT3 activation downregulates the expression of PD-L1 in cancer cells." (PMID 34827136, 2021). "Nevertheless, many agents have been explored for inhibition of STAT3, which is activated in many types of cancer." (PMID 33839684, 2021). "In this context, the STAT3-SLUG pathway mediates the radioresistance via enhancement of cancer stem-like properties and increased EMT-like phenotypes." (PMID 34141616, 2021). "As such, IL-6 production results in autocrine and paracrine activation of STAT3 signaling that promotes survival of cancer cells in response to DNA damage and pro-apoptotic mediators such as TNFα." (PMID 35087822, 2021). "Further research is needed to investigate STAT3 as a predictive biomarker in prognosis and potential clinical therapeutic applications for cancers." (PMID 33382511, 2021).
cancer (continued). "JAK/STAT3 signaling pathway is one of the most promising pathways in cancer stemness research field, which bridges a linkage between ncRNA and m6A in tumorigenesis and metastasis." (PMID 34345203, 2021). "The MYC and STAT3 oncoproteins are widely overexpressed or activated across human cancers and the mTORC1/S6K1 pathway is frequently stimulated in malignancies." (PMID 35095503, 2021). "In various cancers, TYK2 overexpression or GOF mutations lead to STAT1 or STAT3 activation and upregulation of anti-apoptotic proteins, including B-cell CLL/lymphoma-2 (BCL-2) and myeloid cell leukaemia-1 (MCL-1)." (PMID 34439323, 2021). "In recent years, there have been many reports of STAT3 overexpression has been found in cancer cells." (PMID 34679602, 2021). "One of the target factors of RES is signal transducers and activators of transcription 3 (STAT3), an important transcription factor in several cancers, including breast cancer." (PMID 34488773, 2021). "Apart from this, cryptotanshinone can exert its anti-cancer activity via inactivating STAT3 and ERK." (PMID 34575983, 2021). "Previous literature has demonstrated that STAT3 is abnormally activated in a variety of human cancers." (PMID 34356663, 2021). "STAT1, STAT3, and STAT5 are widely studied in the cancer context, among which STAT3 stands in the forefront." (PMID 34771643, 2021). "The miRNAs miR-193a, miR-210, and miR-5100 are transferred by exosomes derived from bone marrow-derived mesenchymal stem cells (BMSCs) to neighbouring cancer cells, thereby activating STAT3 signalling and promoting cancer cell invasion and EMT." (PMID 34193120, 2021). "A resveratrol–caffeic acid hybrid was detected to affect and inhibit acetylation, as well as the phosphorylation of STAT3 on tyrosine residue T705, in two human cancer cell lines." (PMID 34299258, 2021). "Targeting oncogenic transcription factors by polyphenols has recently been inferred, and inhibition of JAK/STAT3 transducing events by EGCG has been reported in numerous cancers." (PMID 33801973, 2021). "In line with the typical signalling of cytokines in the IL6-like family, STAT3 is a central orchestrator of most of the known effects of IL11 in cancer, including promotion of cell growth and survival." (PMID 34834425, 2021). "circFAT1 coordinately controlled cancer stemness and immune evasion through promoting STAT3 activation." (PMID 34258151, 2021). "The implication of STAT3 in the acquired radioresistance of cancer cells has been further demonstrated by several studies that analyzed the relationship between STAT3 and the ability of tumors to regrow after the treatment with IR." (PMID 34141616, 2021). "Combination treatment of curcumin and cisplatin managed to inhibit phosphorylation of JAK and STAT3 in ovarian and papillary thyroid cancer cells leading to enhanced proliferation and reduced stemness of potential cancer stem cells (Khan AQ." (PMID 34867402, 2021). "We also looked at the expression of STAT3 and pSTAT3, pERK1/2 and pAKT whose expression is crucial in key cancer signaling pathways and that have become potential targets for treated GB." (PMID 34067120, 2021). "Expression of HNF4α forms an HNF4α-STAT3 feedback regulatory loop that regulates the course of carcinoma." (PMID 33462379, 2021). "Increased expression of IL-6 and STAT3 was demonstrated in biopsies from UC patients with active disease and in IBD-associated carcinomas, as compared to patients with inactive disease or controls." (PMID 34884543, 2021). "Immunohistochemical (IHC) staining results showed that STAT3 was highly expressed in carcinoma tissues compared with that observed in the non-carcinoma tissues." (PMID 33972660, 2021). "The link between STAT family proteins and carcinoma in humans is well demonstrated, and constitutively activated STAT3 is crucial for carcinogenesis." (PMID 33462379, 2021).
cancer (continued). "Growing studies have revealed that the inactivation of PTEN gene enhances the activation of PI3K/Akt and JAK2/STAT3 pathway, which in turn leads to the initiation, and malignant progression of cancers." (PMID 32626519, 2020). "Several compounds were targeting the PI3K/AKT pathway, such as rigosertib, MK-2206, AZD6482, TGX-221, NVP-BEZ235, and targeting the JAK/STAT pathway, like ruxolitinib and AZD1480, which were significantly correlated to STAT3 expression in cancer cell lines." (PMID 32486001, 2020). "The secreted cytokines from macrophages can trigger PI3K/AKT/mTOR signaling pathway and also lead to the activation of NFKB as well as STAT3 in cancer cells." (PMID 32883235, 2020). "There are seven members of STAT proteins and STAT3 is of importance due to its role in affecting genes involved in cancer progression and malignancy." (PMID 32545648, 2020). "Its expression is regulated by STAT3 and NF-κB transcription factors, which are both activated in a variety of cancers playing critical roles in the regulation of cell proliferation, invasion, apoptosis, and tumorigenesis." (PMID 33382770, 2020). "Nevertheless, we independently demonstrated that STAT3 signaling, a common target in cancers, was efficiently targetable by Benz." (PMID 32102440, 2020). "We then assessed the expression level of the STAT3/MSK1/NFATc2 axis across 31 cancer cohorts available through the TCGA and the Genotype-Tissue Expression (GTEx) dataset." (PMID 32041943, 2020). "B7-H3 was shown to influence tumor progression by regulating the relative molecules via JAK2/STAT3 pathway in several types of cancer 35-37." (PMID 32398947, 2020). "Lowering STAT3 levels also negatively affects the angiogenesis process (by inhibiting VEGF) depriving cancer cells of nutrients." (PMID 32850012, 2020). "Studies have demonstrated that the JAK/STAT3 signaling pathway contributes to cell survival and chemotherapeutic resistance in cancers." (PMID 32756004, 2020). "Stat3 is present in an inactive state in the normal cells, while it is in a continuously active state in a variety of cancer cells." (PMID 32258099, 2020). "STAT3 has been shown to play a key role in the promotion of cancer by mediating proliferation, survival, invasion, and metastasis." (PMID 32630675, 2020). "Recent studies have begun to focus on the post-translational modification of STAT3 as a therapeutic target for cancer treatment." (PMID 32731620, 2020). "Our results showed that eIF4B protein was regulated by STAT3 in a variety of cancer cells, and eIF4B downregulation itself had little effect on cap‐dependent translation." (PMID 32495998, 2020). "The inhibition of STAT3 in cancer is highly desirable and a lot of effort is invested towards the therapeutic inhibition of STAT3 in academia and the pharmaceutical industry." (PMID 32807795, 2020). "Nonetheless, post-translational modifications activated downstream of cytokines, growth factors and oncogenes shape the sub-cellular localization and activities of STAT3 both in cancer and normal cells." (PMID 32331320, 2020). "Other studies suggest that IL-10 stimulates the EMT process and increases proliferation in cancer cells via a STAT3-NF-κB-IL-10 signaling axis." (PMID 32222879, 2020). "This is particularly important since Stat3 and Bcl-xL are known to be involved in the chemoresistance of cancer cells." (PMID 31952197, 2020). "Recent study indicated that the crosstalk between STAT3 pathway and β-catenin signaling contributes to cancer stem cells." (PMID 32887217, 2020). "Here, we posit the inter-connected transcriptional and mitochondrial roles of STAT3 as a mechanistic linchpin between cellular transformation and eventual cancer progression using adipose tissue as a case study." (PMID 32331320, 2020).
cancer (continued). "After initial activation of JAK/STAT3 in high-grade intraepithelial lesions, development of cancer shifts those changes." (PMID 32308553, 2020). "Compared with normal tissues, most kinds of cancer would display a lower protein expression of STAT3." (PMID 32486001, 2020). "Although to a much lower extent than regular NANOG, expression of the human-specific NANOGP8 retrogene, often expressed in human cancers, was also slightly induced by the reprograming process in a STAT3-dependent manner." (PMID 32580970, 2020). "Further, by analyzing gene expression profiles of cancer lines derived from a range of tissues, we report a STAT3-dependent gene set that is predictive of susceptibility to PARP inhibition of blood and other types of cancer." (PMID 33002095, 2020). "Earlier research in curcumin, a natural phenol, has inhibited cancer stem cells via downregulation of STAT3 which is also observed in the cells that were treated with THTMP." (PMID 32164385, 2020). "Our findings indicate that TCN, as a potent inhibitor of STAT3, has promising therapeutic value for cancer treatment and deserves further exploration." (PMID 32422984, 2020). "Overall, we suggest that mLST8 constitutes a potential target for cancer therapy as a cross‐road between STAT3 and the mTOR pathway." (PMID 32495998, 2020). "STAT3 is dispensable for the initial growth of carcinogenesis but it is critical for cancer immune evasion." (PMID 32483429, 2020). "Increased activation of STAT3 in cancer cells results in its continuous presence in the cell nucleus and gene expression disorder." (PMID 33158194, 2020). "By regulating the expression of numerous oncogenic genes, STAT3 promotes the development of different types of cancer." (PMID 32041943, 2020). "Signal transducer and activator of transcription 3 (STAT3) is constitutively activated and overexpressed in many cancers, including non–small‐cell lung cancer (NSCLC)." (PMID 32022328, 2020). "On the other hand, the signal transducer and activator of transcription 3 (STAT3), which dimerizes and translocates into the nucleus after activation, functions as a crucial link between inflammation and cancer." (PMID 32784751, 2020). "A recent study suggested that the proteasome inhibitor YSY01A downregulates gp130 and the activation of JAK2 and STAT3 through a lysosome-autophagy pathway in cancer cells." (PMID 32581853, 2020). "Similar to the antiproliferative effect of STAT3 knockdown on various cancer cells, STAT3 siRNA treatment of HCT116 or MDA‐MB‐231 cells led to a decrease in cell proliferation." (PMID 32495998, 2020). "In recent years, STAT3 has been found to be constitutively activated in multiple types of human cancers, indicating that STAT3 is a valuable target for cancer therapy." (PMID 33681184, 2020). "Since then,various studies have been carried out, confirming STAT-3 as a cancer drug target,and significant work has focused on the discovery of novel STAT-3 inhibitors." (PMID 32167126, 2020). "In cancer, constitutive activation of STAT3 increases the transcription of cell cycle regulators, such as c-Myc and cyclin D, and promotes cancer cell proliferation." (PMID 32300189, 2020). "Previous studies by our and other's laboratories have shown that inhibition of STAT3 down-regulated HSP90 expression in cancer cells." (PMID 32754441, 2020). "Here, we demonstrate that the improved muscle mass and strength upon administration of ACVR2B/Fc was also associated with improvement in Stat3 phosphorylation, further highlighting Stat3 as a pivotal prognosticator of cancer‐induced muscle wasting." (PMID 33200567, 2020). "Upon nuclear translocation, the STAT3 signaling pathway contributes to an enhancement in the proliferation, metastasis and migration of cancer cells." (PMID 32545648, 2020).